TOLLIP (toll interacting protein)
Diseases named in the same sentence as TOLLIP in open-access papers (continued):
Sharing a sentence is not in itself a finding about the gene and the disease.
celiac disease (2 papers, 2012 to 2014). An autoimmune genetic disorder with an unknown pattern of inheritance that primarily affects the digestive tract. "Altered gene expression of TLR2 and 9, as well as, an inhibitory adaptor protein Toll interacting protein or TOLLIP in small intestinal biopsies in celiac disease suggests that microbiota-associated factors may be important in the development of the disease." (PMID 23016134, 2012).
colitis (2 papers, 2016 to 2022). Inflammation of the colon. "The finding that TOLLIP is expressed at a lesser level in L-IECs of C57BL/6 mice than in those of BALB/c mice may reflect the observation that C57BL/6 mice are more sensitive to DSS-induced colitis than BALB/c mice." (PMID 27741296, 2016).
cutaneous leishmaniasis (2 papers, 2015 to 2017). Leishmaniasis affecting the skin. "In this study, we tried to understand why some individuals develop cutaneous leishmaniasis while other in the same area do not by genotyping two polymorphisms situated the TOLLIP gene and we saw that both polymorphisms are associated with cutaneous leishmaniasis." (PMID 26107286, 2015). "The polymorphisms rs5743899 and rs3750920 in the TOLLIP gene were genotyped by polymerase chain reaction and restriction fragment length polymorphism (RFLP) analysis in 631 patients with cutaneous leishmaniasis (CL) caused by L. guyanensis and 530 individuals with no history of leishmaniasis." (PMID 26107286, 2015).
diabetes (2 papers, 2013 to 2020). "Overexpression of TOLLIP in diabetes was yet another possible mechanism for inhibition of TLR2- and TLR4-mediated NFκB activation." (PMID 23149823, 2013).
idiopathic interstitial pneumonia (2 papers, 2013 to 2017). A class of diffuse lung diseases that typically affect the pulmonary interstitium, although some also have a component affecting the airways (for instance, Cryptogenic organizing pneumonitis). "IPF GWAS performed in Japanese and European individuals have identified genetic risk loci within TERT, TOLLIP/MUC5B, and SPPL2C; a GWAS of the broader phenotype idiopathic interstitial pneumonia identified an association within the MUC5B promoter that was also associated with IPF." (PMID 28774304, 2017).
injury (2 papers, 2022 to 2024). Damage inflicted on the body as the direct or indirect result of an external force, with or without disruption of structural continuity. "More interestingly, we found putative SOX9-binding domains in the promotor of the Toll-interacting protein (TOLLIP), an inflammation-regulating factor that has been determined to exhibit protective effects on PQ-AKI and PQ-induced lung injury in our previous works." (PMID 35720190, 2022).
kidney injuries (2 papers, 2021 to 2022). "Similar with our prior study, TOLLIP also showed a protective role in PQ-induced kidney injury." (PMID 34335089, 2021). "Specifically, TOLLIP suppressed TLR2/4-NF-κB signaling to protect against PQ-induced NLRP3 inflammasome activation, thus attenuating kidney injuries." (PMID 35720190, 2022).
malaria (2 papers, 2017 to 2025). Malaria is a serious and sometimes fatal disease caused by a parasite that commonly infects a certain type of mosquito which feeds on humans. "The authors report that the TOLLIP rs3750920C allele is associated with protection to malaria while the T allele with susceptibility." (PMID 28288644, 2017). "The association of the TOLLIP rs3750920 T allele with susceptibility to malaria further provides evidence that genetic variations in immune response genes may predispose individuals to malaria." (PMID 28288644, 2017).
necrotizing enterocolitis (2 papers, 2016 to 2017). Necrotizing enterocolitis (NEC) is a devastating disease that affects mostly the intestine of premature infants. "The lower expression of TOLLIP has been observed in necrotizing enterocolitis intestine with the excessive inflammatory response to colonizing bacteria." (PMID 27304828, 2016).
renal cell carcinoma (2 papers, 2022 to 2025). "In this study, we evaluate TOLLIP expression, investigate its correlations with clinicopathological features of renal cell carcinoma, and explore its potential use as a prognostic marker and the target point for targeted immunotherapy in RCC." (PMID 36499030, 2022). "Considering that autophagy inhibitors enhance the properties of currently used second-line agents, such as PD-L1 and mTOR inhibitors, TOLLIP seems to emerge not only as a prognostic factor but also as a potential therapeutic target in renal cell cancer." (PMID 36499030, 2022). "TOLLIP also leads to insensitivity to chemotherapy in renal cell carcinoma by inducing autophagy." (PMID 39735680, 2025).
stress-related disorder (2 papers, 2024). Stress-related disorders are mental health disorders that are a result of an atypical response to both short and long-term anxiety due to physical, mental, or emotional stress. "Most interestingly, although the TOLLIP gene showed a trend-significant association, it is related to inflammation in patients with MDD and stress-related disorders and is more highly expressed in patients with MDD compared to controls, regardless of childhood trauma exposure." (PMID 39020437, 2024).
acute pancreatitis (1 paper, 2025). An acute inflammatory process that leads to necrosis of the pancreatic parenchyma. "In severe acute pancreatitis rats with acute lung injury, notoginsenoside R1 promotes TOLLIP expression by inhibiting miR-128-2-5p, thereby inhibiting the expression of TLR4, MyD88, and NF-κB related pathway proteins and exerting a protective effect." (PMID 39735680, 2025).
AIDS (1 paper, 2021). A syndrome resulting from the acquired deficiency of cellular immunity caused by the human immunodeficiency virus (HIV). "Researchers have also found that the toll-interacting protein (TOLLIP) and mannose-binding lectin 2 (MBL2) genes may also play a vital role in HIV infection and the progression to AIDS." (PMID 34154540, 2021).
Cirrhosis (1 paper, 2021). A chronic disorder of the liver in which liver tissue becomes scarred and is partially replaced by regenerative nodules and fibrotic tissue resulting in loss of liver function. "Patients with decompensated cirrhosis presented a more limited alteration in TLR signalling genes, including 6 of the 17 upregulated genes observed in compensated cirrhosis, SIGIRR, IRAK1, HSPA1A, TOLLIP and ELK1, as well as downregulation of IL-1B." (PMID 34774066, 2021).
Crohn disease (1 paper, 2019). A gastrointestinal disorder characterized by chronic inflammation involving all layers of the intestinal wall, noncaseating granulomas affecting the intestinal wall and regional lymph nodes, and transmural fibrosis. "In both active and inactive ulcerative colitis and Crohn’s disease, the amount of PPARγ and TOLLIP were attenuated at both transcription and translation levels." (PMID 31011554, 2019).
cutaneous lupus erythematosus (1 paper, 2025). An autoimmune disorder that manifests as different lupus-specific skin disorders; it can occur with systemic lupus erythematosus, or as a singular disease. "Importantly, the molecular docking study further confirmed that afimetoran binds strongly to both mutant and wild type TOLLIP protein, and afimetoran has been recently reported in clinical study of Cutaneous Lupus Erythematosus, as toll like receptor 7/8 (TLR7/8) antagonist." (PMID 41231851, 2025).
endotoxemia (1 paper, 2025). "In endotoxemia, PHLDA1 inhibits pro-inflammatory responses by repressing the TLR4/MyD88/NF-κB pathway through TOLLIP." (PMID 39735680, 2025).
liver inflammatory diseases (1 paper, 2021). "Moreover, IL1RAP and TOLLIP, involved in cytokine–cytokine interaction and Toll-like receptor signaling pathways, have been reported to play a key role in liver inflammatory diseases." (PMID 34829865, 2021).
melanoma (1 paper, 2016). A malignant, usually aggressive tumor composed of atypical, neoplastic melanocytes. "Given that TOLLIP, EPS15, and TAX1BP1 were isolated from a human melanoma cell line using a proteomic approach, it stands to reason that other vesicle-associated adaptor proteins expressed in other cell types could exhibit a similar relationship with RNF26." (PMID 27368102, 2016).
parasitic infection (1 paper, 2020). "Genetic variants of interest identified in several immune related genes for all the antibody response and parasitic infection traits: IBDV (TOLLIP, ANGPTL5, BCL9, THEMIS2), MDV (GRM7), SG (MAP3K21), Eimeria (TOM1L1), and cestodes (TNFAIP1, ATG9A, NOS2)." (PMID 33193617, 2020).
Plasmodium vivax malaria (1 paper, 2017). Malaria resulting from infection by Plasmodium vivax. "In this study, TOLLIP variants were investigated to their relation to Plasmodium vivax malaria in the Brazilian Amazon." (PMID 28288644, 2017).
pulmonary TB (1 paper, 2020). "Our results were also differing from our previous study, which demonstrated that polymorphisms in TOLLIP affected the risk of pulmonary TB." (PMID 32648572, 2020).
triple-negative breast carcinoma (1 paper, 2022). An invasive breast carcinoma which is negative for expression of estrogen receptor (ER), progesterone receptor (PR), and human epidermal growth factor receptor 2 (HER2). "In triple-negative breast cancer, TOLLIP-mediated autophagy can hinder disease progression via the degradation of transmembrane protein 63A (TMEM63A), a novel oncogene that promotes cancer cell proliferation in triple-negative breast cancer." (PMID 36499030, 2022).
infection (18 papers, 2011 to 2025). The state of being infected such as from the introduction of a foreign agent such as serum, vaccine, antigenic substance or organism. "Variants like TOLLIP rs5743890 and rs3750920 are associated with altered lung microbiota, increased susceptibility to infection-triggered exacerbations, and differential responses to antioxidant or antifibrotic therapy." (PMID 41465275, 2025). "Upon grass carp reovirus (GCRV) infection, TOLLIP expression increases significantly in tissues and cells." (PMID 40938946, 2025). "Our data proved that ubiquitinated ACE2 serves as a new substrate for TOLLIP-mediated selective autophagic degradation to influence the infection of SARS-CoV-2 in a ubiquitin signal dependent way." (PMID 36057605, 2022). "DEGs were determined by comparing the transcriptomes of SARS-CoV-2-infected cells with TOLLIP depletion with that of scramble siRNA-treated infection group as control." (PMID 36057605, 2022). "Similar to WT STm infection, genes involved in the regulation of immune responses (ATF3, BATF3, ETS2, IRF9, NFκB2, MAFA, TNFAIP3), effector functions, (CCL4, CD200L, CD40, CD72, CD80, IL18) and TLR signaling, (EAF2, TLR15, TRAF3IP2, TOLLIP) were upregulated after ΔprgH STm infection in both models." (PMID 37854334, 2023). "In this study, components of Toll pathway such as Spätzle, Myd88, cactus, and toll-interacting protein showed a downregulated expression in response to B. thuringiensis with Spätzle showing an 8-fold downregulation at the early stage of infection 6 h postinfection, compared to the control." (PMID 30498450, 2018). "Compared to infection with ASFV-Δ4R, infection with ASFV-WT increased the interaction between endogenous cGAS and TOLLIP in PAMs." (PMID 40618140, 2025). "Human TOLLIP stabilizes resting-state STING while acting as an autophagy receptor for viral proteins, facilitating infection-induced STING degradation." (PMID 40938946, 2025). "In this manner, genes that encode negative regulators of TLR-mediated signaling, such as TOLLIP (Toll-interacting protein) and the lymphocyte antigen 86 (LY86) known as MD1, were up-regulated 6 h after infection." (PMID 22235359, 2012). "Importantly, a genetically guided approach is emerging: stratifying patients according to TOLLIP or TLR polymorphisms may assist in identifying those most likely to benefit from specific immune modulators, reducing the risk of broad immunosuppression and its associated infections." (PMID 41465275, 2025).
cancer (12 papers, 2013 to 2025). A tumor composed of atypical neoplastic, often pleomorphic cells that invade other tissues. "For the first time, they have identified SLC4A7 (sodium bicarbonate cotransporter) and TOLLIP (Toll interacting protein) as novel tyrosine kinase substrates associated with cancer development providing valuable insights into the disease progression." (PMID 23586059, 2013). "Other reports have shown that TOLLIP is associated with cancer-promoting processes." (PMID 39735680, 2025). "TOLLIP is involved in the malignant process of cancers, and it is closely connected with the bad prognosis of cancer patients." (PMID 39735680, 2025). "Mechanistically, we found that miR-3124-5p secreted by CAFs exerts a pro-cancer effect by inhibiting TOLLIP expression and promoting the TLR4/MyD88/NF-κB signaling pathway." (PMID 39735680, 2025). "Functional salvage tests were performed to determine whether CAF-exosome-derived miR-3124-5p plays a pro-cancer role in NSCLC by affecting the TOLLIP signalling pathway." (PMID 39735680, 2025). "Lower levels of SIGIRR and of TOLLIP, NFRKB, TNFRSF1A, and CD14 and of two distinct MAP kinases were detected in all the cancer cell lines analyzed; on the contrary, IRAK1 and HSPD1 mRNAs were upregulated in all the tumor cells." (PMID 35814450, 2022). "These questions include whether CAF-derived exosomal miR-3124-5p regulates genes other than TOLLIP to play a pro-cancer role and whether CAF-derived exosomes contain miRNAs other than miR-3124-5p to inhibit TOLLIP, which require further research." (PMID 39735680, 2025). "EGCG can upregulate Tollip (Toll-interacting protein) and down-regulate of TLR4 expressions via 67LR may be effective in the anti-cancer activity." (PMID 30213077, 2018).
tumor (10 papers, 2015 to 2025). "TOLLIP expression in NSCLC tumour tissues was markedly lower than that in adjacent tissues (a decrease of 70%)." (PMID 39735680, 2025). "In contrast, TOLLIP ablation in mice resulted in reduced tumor incidence, smaller lesions, and reduced tumor cell turnover, suggesting that high TOLLIP levels favor the development of CAC." (PMID 36499030, 2022). "This altered expression pattern is probably due to the downregulation of the ubiquitin-binding protein Toll-interacting protein (TOLLIP) in tumor lesions." (PMID 33321934, 2020). "The phosphorylation event promotes GAT-dependent association of TOM1L1 with the sorting protein TOLLIP and trafficking of the metalloprotease MT1-MMP from endocytic compartments to invadopodia for tumour cell invasion." (PMID 26899482, 2016). "TOLLIP expression in tumor samples was evaluated using the H-score." (PMID 36499030, 2022). "Therefore, the underexpression of TOLLIP in the TMA group might have occurred during tumor immunoediting in the early stages of RCC when TOLLIP-mediated autophagy is still an efficient way of preserving the genome stability and preventing malignant transformation." (PMID 36499030, 2022).
infectious disease (4 papers, 2013 to 2025). A disorder directly resulting from the presence and activity of a microbial, viral, or parasitic agent in humans. "Taken together, these studies demonstrated that polymorphisms in the TOLLIP gene were related to infectious diseases." (PMID 34154540, 2021). "Polymorphisms in the TOLLIP gene are associated with infectious diseases." (PMID 26107286, 2015).
Bacterial infections (3 papers, 2013 to 2021). "Pathway analysis revealed multiple related functions of the new features, such as Viral mRNA Translation (INMT), GABA receptor binding (GABARAP), Bacterial infections in CF airways (TOLLIP), signaling (RALGDS) and others." (PMID 34302024, 2021).
colon (1 paper, 2022). "Higher levels of TGF-β and lower levels of IL-1β, CD14, and CCR5, markers of circulating neutrophils, suggest that TOLLIP deficiency may facilitate the resolution of chronic inflammation during colon carcinogenesis." (PMID 36499030, 2022).
TOLLIP also shares sentences with these, for which no sentence is quoted: Alzheimer disease (3 papers); acute kidney injury (2); autoimmune disease (2); leishmaniasis (2); Nasu-Hakola disease (2); psychiatric disorder (2); rheumatoid arthritis (2); adenoma (1); amyotrophic lateral sclerosis (1); anaphylaxis (1); asthma (1); autism (1); autoimmune disorders (1); cardiac arrest (1); chronic obstructive pulmonary disease (1); Cognitive impairment (1); colon cancers (1); colonic carcinoma (1); Cryptococcus neoformans infection (1); cystic fibrosis (1); gastric cancer (1); hypersensitivity pneumonitis (1); Hypertension (1); inflammatory bowel disease (1); inflammatory skin disorder (1); latent infection (1); lepromatous leprosy (1); metabolic disease (1); myocardial hypertrophy (1); myocardial infarction (1).
A further 15 diseases each share a sentence with TOLLIP in 1 paper.